RETN (resistin)
Diseases named in the same sentence as RETN in open-access papers (continued):
Sharing a sentence is not in itself a finding about the gene and the disease.
Insulin resistance (continued). "Intermittent hypoxemia during sleep increases selenoprotein P, which is one of the hepatokines, as well as TNF-α, CCL-2, and resistin, members of adipokines, to induce insulin resistance via direct cellular mechanisms." (PMID 38893645, 2024). "The adipokine resistin, which is released by visceral fat, plays a role in insulin resistance and chronic inflammation, therefore exacerbating cardiovascular health." (PMID 39335642, 2024). "Adipokines such as leptin, resistin, and retinol-binding protein 4 increase insulin resistance, whereas adiponectin with anti-inflammatory and antilipogenic effects increases insulin sensitivity." (PMID 39065815, 2024). "On the other hand, in mice expressing human resistin, glucose tolerance and hepatic insulin resistance have been demonstrated under chronic inflammatory conditions, as well as an increased production of pro-inflammatory cytokines (TNF-α, IL-1, and MCP-1)." (PMID 38275812, 2024). "Leptin, adiponectin, and resistin are key markers, along with pro-inflammatory cytokines like TNFα, IL-1β, and IL-6, which also play roles in insulin resistance." (PMID 39407941, 2024). "Our data show reduced expression levels of Resistin corelated with upregulated Rida (reactive intermediate imine deaminase A homolog), which was previously shown as repressed in insulin resistance." (PMID 38473844, 2024). "Previous research has indicated that a high resistin level impairs glucose tolerance, increases insulin resistance in the liver, and impairs insulin activity." (PMID 39125415, 2024). "Additionally, excessive visceral fat may result in an increased production of adipocytokine (resistin, leptin, adiponectin), which are closely associated with heightened insulin resistance and compromised β-cell efficiency, leading to elevated blood glucose levels." (PMID 39064720, 2024). "Despite its unclear involvement in obesity and insulin resistance, human resistin plays a crucial role in immune cell recruitment and proinflammatory cytokine release." (PMID 38562275, 2024). "ADPN and resistin can regulate insulin sensitivity and reduce glucose output and insulin resistance." (PMID 37569125, 2023). "Our results revealed that patients with BMI > 25 kg/m2 had higher concentrations of serum levels of resistin, chemerin and visfatin, insulin resistance-markers and serum levels of inflammatory cytokines, compared with patients with BMI > 25 kg/m2." (PMID 36830883, 2023). "Only one study investigated the effects of PDB extracts on the kidney, showing that PDB significantly reduced the mRNA expression of resistin in perirenal adipose tissue of rats to reduce insulin resistance." (PMID 37849729, 2023). "In vitro studies using 3T3-L1 adipocyte cell line showed that resistin neutralization by resistin antiserum enhanced insulin-stimulated glucose uptake and decreased insulin resistance." (PMID 38136564, 2023). "In the C57BL/6J obese mice model, luteolin (10 mg/kg) reduces MCP-1 and resistin in blood, while elevated adiponectin level that improved insulin resistance (IR) and T2DM." (PMID 37229273, 2023). "Subsequently, high levels of resistin correlate with insulin resistance, glucose intolerance, and endothelial dysfunction marker concentration." (PMID 38139276, 2023). "On the other hand, elevated resistin concentration is involved in the pathogenesis of inflammation and the development of insulin resistance, type 2 diabetes, hypertension, atherogenic dyslipidemia and atherosclerosis." (PMID 36835557, 2023). "Other proteins related to insulin resistance and insulin sensitivity such as resistin and adiponectin levels were also determined." (PMID 37108530, 2023). "In a transgenic mouse model expressing human resistin exclusively, the adipose tissue inflammation was exacerbated, and lipolysis and free fatty acid accumulation increased, contributing to insulin resistance." (PMID 38136564, 2023).
Insulin resistance (continued). "Leptin and resistin are inflammatory cytokines involved in the development of insulin resistance, whose levels increase with body fat mass." (PMID 37576981, 2023). "Diabetes can be efficiently treated with curcumin by increasing insulin resistance and decreasing leptin, resistin, and insulin levels." (PMID 37240220, 2023). "It has been found that resistin levels show a positive correlation with fat mass, insulin resistance, and interleukin 6 (IL-6)." (PMID 37763771, 2023). "Not only is metformin effective at reducing insulin resistance and hyperglycaemia, but it also decreases circulating leptin and resistin, whilst leading to an increase in adiponectin." (PMID 36983885, 2023). "HHcy is also a factor affecting insulin resistance, because HHcy can mediate the expression and secretion of resistin as well as certain inflammatory factors." (PMID 36839194, 2023). "IL-33 plays protective roles via various mechanisms: it inhibits resistin synthesis and thus inhibits insulin resistance and T2DM development." (PMID 37762140, 2023). "It was initially identified in mice as a protein that appeared to induce insulin resistance, hence its name, “resistin”." (PMID 37893945, 2023). "The effects of resistin on insulin resistance are not fully understood; however, it appears to influence beta cell apoptosis and insulin receptor expression." (PMID 37761031, 2023). "Of note, it was reported that HFD-induced obese mice exhibited increased plasma levels of resistin while immunoneutralization of circulating resistin in these animals improved insulin resistance." (PMID 38136564, 2023). "Recombinant resistin administration to normal animals produce insulin resistance, however, immune neutralization of resistin improves insulin sensitivity in obese animals with insulin resistance." (PMID 37014444, 2023). "Excessive fat tissue is a source of adipokines, such as resistin, which leads to insulin resistance." (PMID 36983908, 2023). "There is a demand for new studies focusing on the direct role of resistin in the pathogenesis of insulin resistance and its interactions with the cells of the immune system." (PMID 36235636, 2022). "Among the reported effects is the reduction of insulin resistance by suppressing the secretion of the adipocytokine resistin." (PMID 36233611, 2022). "Enriched diet with EPA/DHA reduced TNF-α, C-peptide, insulin resistance, resistin, and the plasma atherogenic index, but increased TC, LDL-c, VLDL-c, and TG without changes in HDL-c." (PMID 35036426, 2022). "Correlation analyses between the resistin and insulin resistance were conducted in the total group and the four subgroups." (PMID 34996484, 2022). "High glucose levels can increase MALAT1 expression in endothelial cells and MALAT1 up-regulates resistin to reduce insulin resistance during exercise." (PMID 35163020, 2022). "According to the literature, resistin induces insulin resistance through insulin antagonization, which reduces glucose absorption and metabolism by adipocytes, muscle cells, and other tissues." (PMID 36262532, 2022). "Although a few studies have reported a positive correlation between resistin levels and insulin resistance, this issue needs to be addressed in larger human studies in different ethnic populations." (PMID 35629157, 2022). "Hypertrophic adipocytes produce abnormal adipokines and cytokines, such as TNF-alpha, MCP-1, FFA, IL-6, and resistin, which inhibit insulin signaling in hepatocytes and induce insulin resistance." (PMID 36615686, 2022). "The year 2001 appears to be the first time when resistin was described as a peptide released by adipocytes, responsible for the development of insulin resistance." (PMID 36235636, 2022). "Plasma concentrations of resistin were higher in genetic and diet-induced obese mice with insulin resistance." (PMID 36612600, 2022).
Insulin resistance (continued). "One possible mechanism behind this theory is that aerobic exercise uses fat as the main source of energy to reduce adipose tissue mass, decrease resistin concentrations and increase adiponectin secretion, which results in improved insulin resistance." (PMID 35354451, 2022). "Risk factors for diabetic nephropathy as well as comparisons between resistin and insulin resistance were investigated by logistic regression analysis." (PMID 34996484, 2022). "In this study, serum resistin, TNF-α, and leptin levels were dramatically reduced by SRPE-3-Cr(III) treatment, indicating SRPE-3-Cr(III) alleviated insulin resistance by inhibiting the secretion of serum resistin, leptin, and TNF-α from adipocytes." (PMID 37073221, 2022). "Adiponectin, the most crucial insulin-sensitizing, anti-inflammatory adipokine, and resistin, a newly discovered adipokine directly related to insulin resistance, are the main adipokines influenced by obesity." (PMID 36355818, 2022). "Individuals with hyperthyroidism have higher resistin levels, and excess thyroid hormone levels induce insulin resistance in the liver and surrounding tissues." (PMID 36686437, 2022). "Compared with insulin resistance, resistin had a closer relationship with renal complications in the SIRD group based on ROC curve analysis." (PMID 34996484, 2022). "In vitro recombinant resistin treatment induces insulin resistance in a variety of cells, including adipocytes, skeletal muscle cells, and hepatocytes." (PMID 35909571, 2022). "MALAT1 has also been shown to regulate hyperglycemia-induced inflammatory processes in endothelial cells, and inhibition of MALAT1 down-regulates resistin to reduce insulin resistance by exercise." (PMID 35163020, 2022). "Although leptin, TNF-α, resistin, and adiponectin are all representative adipokines, the first three are positively correlated with insulin resistance and adiponectin is negatively correlated." (PMID 37073221, 2022). "Simultaneously, resistin additionally has the traits of proinflammatory cytokines and is involved in insulin resistance, inflammation, and immune regulation." (PMID 36686437, 2022). "Among recently described adipokines, resistin has been proposed as a proinflammatory link between insulin resistance and obesity." (PMID 36501122, 2022). "Although the role of resistin in pro-inflammatory processes has been demonstrated in several studies, the role of resistin in insulin resistance in humans remains controversial." (PMID 35629157, 2022). "L‐14 extract significantly decreases resistin (an inflammation and insulin resistance marker) and serum LDL‐c, total cholesterol, and TAG levels." (PMID 33830560, 2021). "In another study, researchers reported that exercise reduced insulin resistance in type 2 diabetes mellitus via mediating the lncRNA MALAT1/microRNA-382-3p/resistin axis." (PMID 34284789, 2021). "Resistin, PAI-I, and adiponectin are adipokines that are associated with insulin resistance/insulin sensitivity." (PMID 33705641, 2021). "Human studies have shown that individuals with severe insulin resistance have higher resistin levels than healthy individuals." (PMID 35011183, 2021). "Our study identified increased leptin and resistin levels in HFCD rats suggesting the presence of insulin resistance." (PMID 34037093, 2021). "In conclusion, we report, for the first time to our knowledge, that resistin-induced insulin resistance and neuroinflammation are potentiated by neuronal exposure to palmitic acid and strongly attenuated by DHA treatment." (PMID 33686181, 2021). "Leptin and resistin are the proinflammatory cytokines that promote insulin resistance via diverse mechanisms." (PMID 33917607, 2021). "In humans, the relationship between resistin level and the development of insulin resistance is ambiguous." (PMID 34947881, 2021).
Insulin resistance (continued). "It has been assumed that resistin participates in the development of myocardium dysfunction via the promotion of insulin resistance and inflammation, but one study exists that suggests a different mechanism, independent of these factors." (PMID 34679472, 2021). "We have reported that resistin was able to activate neuroinflammation and to promote insulin resistance through its binding to TLR415." (PMID 33686181, 2021). "In rats, resistin induces insulin resistance, but its effects on insulin sensitivity remain controversial in humans." (PMID 34037093, 2021). "Resistin is a cytokine involved in chronic inflammatory diseases such as atherosclerosis and insulin resistance." (PMID 34290294, 2021). "Diabetic obese mice treated with TAN at doses of 200 mg/kg experience reductions in body weight, insulin resistance and lowered secretion of key inflammation markers, adiponectin, leptin, resistin, IL‐6, and MCP‐1." (PMID 33841818, 2021). "Resistin is a cytokine that is mainly produced by immune cells and has connections with hypertension, diabetes, insulin resistance, and CVD." (PMID 33797274, 2021). "Curcuminoids have been shown to improve insulin resistance, decrease glucose and insulin levels, increase adiponectin release, and reduce the levels of leptin, resistin, interleukin (IL)-6 IL-1β, and tumor necrosis factor-α in patients with T2DM." (PMID 34012421, 2021). "The increased adipose tissue will lead to metabolic changes, including leptin, resistin, and pro-inflammatory factors, leading to insulin resistance and other cardiovascular and cerebrovascular diseases." (PMID 34867792, 2021). "Resistin is an important factor for insulin resistance; however, its expression reportedly changed in two different directions (increase / decrease) by treatments in different studies." (PMID 33641315, 2021). "In conclusion, the available data indicate that resistin in some way can influence insulin resistance during pregnancy but, most likely, it has a secondary role in the pathogenesis of GDM." (PMID 34652617, 2021). "Following the infiltration of CD8-positive cytotoxic T cells and the phenotypic change to M1 macrophages, inflammatory adipokines including TNF-α, IL-6, and RETN are produced, leading to insulin resistance." (PMID 34884703, 2021). "Many studies have shown adipokines (leptin, adiponectin, resistin, etc.)play an important role in insulin resistance and T2D development." (PMID 33478575, 2021). "Resistin and adiponectin are antagonist molecules, since resistin induces insulin resistance and is considered pro-inflammatory, whereas adiponectin induces insulin sensitivity and is considered protective against inflammation." (PMID 34822574, 2021). "Of particular interest is that in rodents, resistin induces insulin resistance in the metabolically important organ, the liver." (PMID 33679451, 2021). "High levels of resistin can trigger a proinflammatory state by inducing the expression of the proinflammatory cytokines, favoring insulin resistance and enhancing oxidative stress." (PMID 34603198, 2021). "Resistin, an inflammatory cytokine secreted by the adipose tissue, is suggested to have a role in the development of insulin resistance." (PMID 33865458, 2021). "We measured resistin, which is a marker for insulin resistance and observed lower resistin levels in female offspring supplemented with FO either during pregnancy or early life compared to male offspring." (PMID 34835957, 2021). "Metabolic improvements in both groups were also observed for insulin resistance, leptin, plasminogen activator inhibitor-1, and resistin." (PMID 34501456, 2021). "The molecule was named “resistin” to be suggestive for the induced insulin resistance and impaired glucose tolerance observed in mice that underwent treatment with a recombinant form." (PMID 34680059, 2021). "P3DEX also significantly decreased resistin, an adipokine known to increase with inflammation and insulin resistance." (PMID 34093565, 2021).
Insulin resistance (continued). "Administration of recombinant resistin in normal mice resulted in the development of insulin resistance." (PMID 34659568, 2021). "The increase in circulating resistin levels is considered to contribute to the development of insulin resistance and metabolic alterations compatible with those of type 2 diabetes mellitus in rats and humans, but little is known about its role in dogs." (PMID 32966299, 2020). "Among the best characterized activators of JAK signaling in the context of metabolic disorders, certain adipokines, including leptin and resistin, are known to be involved in the pathogenesis of insulin resistance." (PMID 32413585, 2020). "Eriocitrin also improved lipid peroxidation (−19 % at 25 mg/kg and −22 % at 100 mg/kg), and markers of insulin resistance, such as resistin (−15 %) and insulin resistance index (−34 % at 25 mg/kg and −39 % at 100 mg/kg)." (PMID 33489104, 2020). "Although there is no clear answer about the role of resistin in the pathogenesis of insulin resistance in humans, the results of numerous experiments have shown that resistin can play a role in inflammatory processes." (PMID 32375231, 2020). "RA patients with ε2ε3 genotype are associated with lower levels of TNF-α, IL-6, resistin, visfatin, and CVD risk, while RA patients with ε3ε4 genotype exhibited higher levels of LDL-C, insulin resistance, and higher CVD risks." (PMID 33297350, 2020). "Resistin is another adipokine involved in insulin resistance and type 2 diabetes and, in parallel, has pro-inflammatory properties." (PMID 32993784, 2020). "While not providing definitive mechanistic evidence, our data does corroborate a strong relationship between resistin and stress-induced insulin resistance and support a lipolysis-mediated resistin release during acute stress." (PMID 33097799, 2020). "Another signal particle secreted especially by mature adipocytes and affecting the induction of insulin resistance is resistin." (PMID 33322719, 2020). "Analysis of human data showed that the relationship between resistin level and the development of insulin resistance is ambiguous." (PMID 32375231, 2020). "Several studies have shown that in patients with NAFLD, serum resistin levels are correlated with insulin resistance and the severity of steatosis, inflammation, and fibrosis." (PMID 33336025, 2020). "Altered secretions of adipokines such as adiponectin (ADIPOQ), leptin (LEP) and resistin (RETN) by adipose tissues is one of the important contributory factors to insulin resistance, cardiovascular diseases and metabolic disorders." (PMID 32695266, 2020). "Reduced level of adiponectin and increased levels of interleukin-6 (IL-6), tumor necrosis factor-α (TNF-α), free fatty acids, and resistin can reduce insulin-mediated glucose uptake due to insulin resistance." (PMID 32047529, 2020). "Mechanisms by which quercetin suppress insulin resistance include reducing testosterone, LH and resistin levels and increasing adiponectin activity." (PMID 32005271, 2020). "In this study, serum resistin, leptin, and TNF-α levels were dramatically decreased by Pt-PS supplementation, which was associated with the alleviation of insulin resistance." (PMID 32971772, 2020). "In the present study, we also observed a positive correlation of serum resistin level with insulin resistance and NASs in NAFLD rats." (PMID 33336025, 2020). "In our cohort, we found that MR-proANP is strongly correlated with adipocytokines such as adiponectin, RBP4 and resistin, which are important mediators of insulin resistance and metabolic alterations." (PMID 31830996, 2019). "Contrarily, mRNA levels of resistin are decreased in WAT of obese mice, and administration of anti-resistin antibody improved insulin resistance and blood glucose levels." (PMID 31208019, 2019). "Nevertheless, the role of resistin on the development of brain inflammation and insulin resistance remains poorly documented." (PMID 30906281, 2019).